INS (insulin)
Diseases named in the same sentence as INS in open-access papers (continued):
Sharing a sentence is not in itself a finding about the gene and the disease.
type 2 diabetes (continued). "The differentiation was elegantly signified in type 2 diabetes trials in which modest calorie restriction decreased fat in the liver, hepatic insulin sensitivity, and fasting plasma glucose levels improved, but muscular insulin resistance remained unchanged." (PMID 36060389, 2022). "Our study suggests that insulin therapy with tight glycemic control might be an effective treatment for patients with type 2 diabetes and EPI." (PMID 36213198, 2022). "The conceptual paradigm established by the insulin-resistant subgroup with ‘adipose failure’ may have a wider influence on precision therapy for common type 2 diabetes, however." (PMID 35618782, 2022). "We were specifically interested in patients with type 2 diabetes whose standard treatment was ineffective in maintaining adequate glycemic control, and who would thus benefit from access to the newly available drugs before considering insulin-based treatment." (PMID 36143268, 2022). "However, over time most patients with type 2 diabetes also need oral medication and many require insulin treatment." (PMID 36584077, 2022). "Type 2 diabetes (T2D) is a multi-faceted disease, with both genetic and environmental risk factors (Kahn 2003, 2; Langenberg and Lotta 2018; Huang and Hu 2015), which is marked by impaired beta cell function; specifically, defective glucose-stimulated insulin secretion (GSIS)." (PMID 35314868, 2022). "It remains to be determined whether reduced insulin degradation by the liver or oversecretion by beta cells is more important in the development of type 2 diabetes." (PMID 35163746, 2022). "In contrast, adiponectin stimulates insulin function and sensitivity, and its levels are negatively correlated with waist circumference, visceral fat weight, triglycerides and HDL levels, fast glucose and insulin levels, and also with the development of type 2 diabetes." (PMID 35499991, 2022). "Type II diabetes is generally regarded as a progressive disease, with metabolic syndrome and insulin resistance giving way to full-blown type II diabetes, characterized by insufficient insulin production." (PMID 35327470, 2022). "Elevated levels of non-esterified fatty acids (NEFA), characteristic of insulin resistant states such as obesity and type II diabetes, have been proposed to mediate their effects on vascular function by modulating insulin signalling pathways in the endothelium." (PMID 35157107, 2022). "Inhibition of lipolysis through HSL inhibition may provide a mechanism to prevent the accumulation of free fatty acids and to improve the affectability of insulin and blood glucose handling in type II diabetes." (PMID 36530555, 2022). "The main aim of this study was to investigate if the web-based Glucoonline® system is effective in improving overall glucose control, determined by measuring HbA1c levels, in insulin-treated patients with type 1 and type 2 diabetes, as compared to standard of care." (PMID 35476320, 2022). "All physicians agree, without any exceptions, that diabetic patients who presented to the Emergency Department, unconscious and in a hypoglycemic coma, will have insulin promptly withheld, and they would be immediately administered intravenous glucose infusions as a life-saving maneuver." (PMID 36447726, 2022). "Furthermore, three cases demonstrated a prolonged period of survival (coma) between insulin administration and death allowing time for insulin to be degraded, or the administration of rapid-acting insulin which is also rapidly degraded." (PMID 35943711, 2022). "Inhibition of HSL can improve insulin sensitivity and control of blood glucose in type 2 diabetes." (PMID 36530555, 2022). "Magnesium has a significant impact on insulin secretion and may contribute to dysfunction of pancreatic beta cells in type 2 diabetes." (PMID 36423061, 2022).
type 2 diabetes (continued). "While the benefit of CGM on TIR among patients with type 2 diabetes treated with basal insulin is apparent across the range of baseline glycemic control, the greatest impact of CGM is in those with the worst baseline glycemic control, particularly among those with HbA1c ≥10%." (PMID 34962151, 2022). "Diabetes is a metabolic disorders illness caused by the absolute or relative lack of insulin secretion, and type 2 diabetes (T2D) is more common in patients." (PMID 35846275, 2022). "A study of circadian regulation of lipid metabolism in human pancreatic islets reveals that Type 2 Diabetes leads to global and temporal alterations of phospholipid and sphingolipid metabolism in islets, resulting in decreased membrane fluidity and insulin secretion defects." (PMID 35921354, 2022). "C57BL/6 is a commonly used inbred mouse line that responds effectively to HFD by increasing fat and body weight, being insulin-resistant (Type 2 diabetes-like), and transmitting all metabolic alterations to at least two generations as previously indicated (Winzell and Ahrén, 2004)." (PMID 35419033, 2022). "Physical activity, however, is known to have a positive impact on metabolism and it was proven that less active and more obese individuals, such as patients with diabetes type 2, can experience harmful changes which are responsible, for example, for insulin sensitivity and aerobic capacity." (PMID 35072900, 2022). "However, in 2019, a clinical Glucagon-like-peptide-1 (GLP-1) receptor agonist called Rybelsus® (Semaglutide) came into the market that treats Type 2 diabetes by stimulating the secretion of insulin from the pancreas." (PMID 36559303, 2022). "Interestingly, after completing the HIIT-protocol, the men with type 2 diabetes achieved a level of insulin sensitivity and also metabolic flexibility (ΔRER) similar to obese and lean men at baseline." (PMID 36387850, 2022). "Low magnesium (2+) levels lead to defective tyrosine kinase activity, and insulin acts on receptors that are later damaged, altering cellular glucose transport and reducing cellular glucose utilization, thereby promoting peripheral IR in type 2 diabetes." (PMID 35747262, 2022). "However, type 2 diabetics have low insulin sensitivity, impaired glucose tolerance, and decreased insulin-stimulated glucose uptake; therefore, glucose level becomes too high." (PMID 36339572, 2022). "They concluded that “lower MCRI [surrogate for insulin clearance] is related to an unfavourable metabolic phenotype and is associated with incident type 2 diabetes independent of established risk factors”." (PMID 35163746, 2022). "Non-critically ill hospitalized patients with newly diagnosed hyperglycemia or type 2 diabetes, a subcutaneous basal-bolus insulin regimen in combination with a correction insulin scale is safe to administer according to the 2012 Endocrine Society clinical practice guideline." (PMID 35959169, 2022). "After the mice model of type 2 diabetes ate ethanolic extract from the sericin layer for over seven weeks, increased cellular insulin sensitivity and its secretory signaling mediators, improved oral glucose tolerance and insulin tolerance tests, and decreased blood glucose were observed." (PMID 36105465, 2022). "Here, we tested whether restricting energy intake to a feasible, 10 h time frame for 3 weeks would lower hepatic glycogen levels and improve insulin sensitivity in overweight/obese adults with type 2 diabetes." (PMID 35871650, 2022). "Moreover, in a study among type 2 diabetes-free participants, fasting plasma insulin and insulin resistant measures have been positively correlated with O-phosphoethanolamine downstream product phosphatidylethanolamine." (PMID 35086546, 2022). "The search was for randomized, controlled trial studies (RCT) on insulin infusion (CSII) combined with oral hypoglycemic drugs (TZDs/metformin/acarbose/GLP-1 receptor agonist/SGLT-2 inhibitor/DPP-4 inhibitor) in the treatment of type 2 diabetes." (PMID 36015100, 2022).
type 2 diabetes (continued). "In patients with type 2 diabetes, carnitine supplementation may improve insulin sensitivity by increasing the rate of fatty acid oxidation, and glucose metabolism and reducing oxidative stress." (PMID 36120473, 2022). "The effect of physical training on insulin secretion in patients with type 2 diabetes is less well studied, but a few studies have found that the insulin secretory capacity may increase following physical training." (PMID 36531168, 2022). "As long as the beta‐cells manage to increase insulin secretion the glucose plasma levels remain normal or near normal; but when beta‐cell function fails, the plasma glucose concentration starts to rise, leading to the onset of overt type 2 diabetes." (PMID 35913467, 2022). "Chronically high levels of circulating FFAs, in turn, exacerbate metabolic dysfunction, and pharmacological inhibition of lipolysis improves insulin sensitivity and glucose tolerance in subjects with obesity and/or type 2 diabetes and in mouse models of diet-induced obesity." (PMID 35563078, 2022). "Lack of sleep can affect circadian rhythms, reduce insulin sensitivity, increase insulin resistance, and cause catecholamine and cortisol levels to rise, increasing the incidence of type 2 diabetes." (PMID 36110415, 2022). "However, post-training insulin-suppressed LOX was only higher in men with type 2 diabetes compared with lean men." (PMID 36387850, 2022). "However, insulin is the cornerstone of glucose control, especially in patients with type 2 diabetes and beta-cell function failure." (PMID 36463197, 2022). "The high fasting glucose and insulin levels of individuals in the HRBF cluster resemble the β-cell dysfunction characteristic of type 2 diabetes; thus, pharmacological interventions to regulate β-cell function might be effective." (PMID 36253773, 2022). "Incretins reduce glycemic variability (GV) in patients with type 2 diabetes, but it is unknown whether switching from a combination of basal insulin and a DPP-4 inhibitor to insulin degludec/liraglutide (IDegLira) improves GV." (PMID 35097130, 2022). "A meta-analysis of nine controlled studies involving 1178 patients with type 2 diabetes showed that a Mediterranean-style diet led to greater reductions in haemoglobin A1c, fasting blood glucose, fasting insulin, BMI and body weight compared to other approaches such as low-fat diets." (PMID 35458121, 2022). "High-fat diet induces obesity in animals, and low-dose injection of STZ can induce apoptosis of some islet β-cells, resulting in relatively insufficient insulin secretion and abnormal glucose metabolism, thereby simulating the clinical pathogenesis of type 2 diabetes." (PMID 35845316, 2022). "In adult-onset diabetes, t-GADA increase the risk for insulin therapy, indicating that autoantibodies to the M- and C-epitopes might reflect more aggressive beta-cell destruction." (PMID 34747488, 2022). "Therefore, myristic acid improved both insulin-dependent and -independent glucose uptakes in mice with type 2 diabetes." (PMID 36685282, 2022). "Also, the ethanolic leaves extract of A. comosus improved the sensitivity of insulin levels in rats with type 2 diabetes, which relates to enhancing the action of insulin in the hepatic cells." (PMID 36557843, 2022). "Type 2 diabetes mellitus (T2DM) is a hyperglycemic disease caused by insulin resistance and insufficient insulin secretion, which may be caused by obesity and reduced physical activity (International Diabetes Federation (IDF), 2019)." (PMID 36071848, 2022). "However, many patients with type 2 diabetes will eventually require and benefit from insulin therapy." (PMID 35913467, 2022). "In addition, the ability to use insulin and gluconeogenesis in the liver is weakened, resulting in the occurrence and development of type 2 diabetes." (PMID 36079153, 2022).
type 2 diabetes (continued). "Misclassification of type 1 and type 2 diabetes may have occurred in this real-world data set, although the small number of individuals diagnosed with T2D managed with insulin alone (n = 14) suggests the effect of this on our findings would be minimal." (PMID 35587468, 2022). "Increased UCP2 expression can cause a lack of glucose effect on insulin secretion in type 2 diabetes." (PMID 35323702, 2022). "In patients with type II diabetes, therapeutic insulin concentrations reach 30 ng/ml (5.2 nM)." (PMID 34554347, 2022). "In particular, there is evidence that some of these agents may improve muscle or adipocyte insulin sensitivity and glycemic control in type 2 diabetics or those with metabolic syndrome." (PMID 36135209, 2022). "In type 2 diabetes, the body either produces insufficient insulin or the cells reject it." (PMID 36060389, 2022). "Four traits included in this study may be considered as part of the clinical definition of type 2 diabetes or ‘endophenotypes’ of type 2 diabetes, namely fasting glucose, fasting insulin, glucose and HbA1c." (PMID 35129650, 2022). "Type-2 diabetes (hyperglycemia) and obesity (free fat acids—FFA) are closely associated with increased mitochondrial ROS generation, which in turn, decreases the insulin content and glucose-stimulated insulin secretion of β-cells." (PMID 35326098, 2022). "This is paradoxical because it has been reported that Zn may help reduce the onset or progression of type 2 diabetes through a variety of mechanisms involving both insulin secretion and peripheral tissue action." (PMID 36290714, 2022). "Polyphenols may exert pleiotropic health benefits, but they are of particular interest in managing type 2 diabetes due to their anti-inflammatory, antioxidant, insulin-sensitizing and anti-bacterial properties." (PMID 35327570, 2022). "Supplementing exogenous α-Klotho can reduce hyperglycemia injury by promoting glycogen storage, inhibiting gluconeogenesis, improving insulin sensitivity in type 2 diabetes, anti-inflammatory, antioxidant stress, and inhibiting fibrosis; thus, protecting the kidney." (PMID 35692408, 2022). "It results from reduced sensitivity of the target tissues (muscles, adipose tissue, liver) to insulin and may lead to the development of type 2 diabetes." (PMID 35255873, 2022). "In type 2 diabetes (T2D), it is known that INS transcript expression is reduced." (PMID 35399953, 2022). "Type II diabetes is one of the most prevalent metabolic disorders both in low and high-income countries being managed by improving insulin secretion and controlling blood glucose levels by administering oral hypoglycemic drugs such as α-glucosidase inhibitors, sulfonylureas, and biguanides." (PMID 35358239, 2022). "Physical activity stimulates insulin sensitivity and may prevent obesity and subsequent type 2 diabetes." (PMID 35846274, 2022). "Additionally, dietary restriction and lifestyle interventions can restore whole body insulin sensitivity in people with type 2 diabetes." (PMID 35884888, 2022). "Hitherto, it is not known whether TRE could result in a more pronounced depletion in hepatic glycogen levels in type 2 diabetes, leading to an improved insulin sensitivity." (PMID 35871650, 2022). "Although we have shown that miR-21 in islet β cell promotes insulin secretion though Pdcd4-AP-1-Glut2 pathway, whether exosomal miR-21 released by islet β cell regulates insulin resistance and the development of type 2 diabetes warrants further investigation." (PMID 35729232, 2022). "Considering that consumption of Lactobacillus acidophilus improves carbohydrate metabolism in obese subjects and patients with type 2 diabetes, it is feasible that sucralose contributes to the abnormal insulin and glucose behavior by decreasing the Lactobacillus acidophilus population." (PMID 35208888, 2022).
type 2 diabetes (continued). "A prior survey investigating management of type 1 and type 2 diabetes using CGM showed most behavioral responses prompted by CGM data, or alerts were associated with modifications to prandial or corrective insulin dosing or the ability to detect and respond to hypoglycemia." (PMID 34962151, 2022). "In addition, our results demonstrated that genetically predicted long sleep duration was unlikely to be causally associated with coronary heart disease, heart failure, atrial fibrillation, type 2 diabetes, fasting glucose, fasting insulin, or HbA1c." (PMID 36277903, 2022). "Obesity and type 2 diabetes (T2DM) have a negative effect on insulin-stimulated liver GU, whereas weight loss by bariatric surgery (BS) increases liver GU." (PMID 35448508, 2022). "Postprandial glycemia may contribute as much or more than fasting blood glucose to the pathogenesis of impaired insulin sensitivity and insulin secretion seen in the progression towards type 2 diabetes." (PMID 35277067, 2022). "This suggests that β-cells’ ability to functionally compensate in response to insulin demand is a tipping point in determining whether an individual will develop Type 2 Diabetes." (PMID 36672613, 2022). "Since our TRE protocol was feasible and safe, and resulted in improved 24 h glucose levels, it would be interesting to examine the impact of 10 h TRE on glucose homeostasis and insulin sensitivity in type 2 diabetes in the long term to address the clinical relevance of TRE." (PMID 35871650, 2022). "This mendelian randomisation analysis identified evidence supporting causal effects on increasing liver fat of increased adiposity, type 2 diabetes (including raised fasting insulin levels), systolic blood pressure, smoking, alcohol consumption, and sedentary time watching television." (PMID 36936593, 2022). "Therefore, this reduced fasting, postprandial and total insulin secretion, alleviated hyperinsulinemia in overweight or obese type 2 diabetes." (PMID 36307866, 2022). "Metformin is the most prescribed oral antidiabetic agent for individuals with type 2 diabetes (T2D) due to its relative safety, low cost, and multiple beneficial effects on blood glucose, insulin sensitivity, lipid metabolism, cardiovascular mortality and tumorigenesis." (PMID 36304148, 2022). "Since some lean patients with type 2 diabetes may be more insulin sensitive, PI3K-Akt-mTOR pathway could be further stimulated by insulin and IGF-1, compared to in obese patients." (PMID 35351050, 2022). "One of them is exenatide, which stimulates insulin secretion in type-2 diabetes patients." (PMID 36618620, 2022). "Anti-diabetic drugs are broadly divided into non-insulin drugs such as but not limited to: insulin sensitizers (thiazolidinediones), insulin secretagogues (sulfonylureas and glinides), which are used for type 2 diabetes, and insulin analogs which are mainly used for type 1 diabetes." (PMID 36432252, 2022). "In conclusion, it is likely that glucagon test is the most powerful tool for predicting the possibility of insulin withdrawal as well as for evaluating endogenous insulin secretory capacity in subjects with type 2 diabetes requiring hospitalization due to hyperglycemia." (PMID 35574023, 2022). "Treatment of type II diabetes with metformin, which lowers insulin secretion, reduces gastric cancer incidence Type I diabetics have also increased gastric cancer incidence, that reaches 3.3-fold after 15 years of insulin therapy." (PMID 34554347, 2022). "Overnutrition compensation in LBW individuals may cause excessive lipid accumulation, obesity, type II diabetes, and hypertension due to the LBW-specific insulin-resistance state." (PMID 35552417, 2022). "Our findings suggest that such associations are driven in part by pleiotropic effects and in part by causal effects of a genetic predisposition to type 2 diabetes and of fasting insulin on the development of PCOS, which are independent of BMI." (PMID 35771237, 2022).